RPL10A (ribosomal protein L10a)
Description:
Component of the large ribosomal subunit. The ribosome is a large ribonucleoprotein complex responsible for the synthesis of proteins in the cell.
Synonyms: NEDD6; Csa-19; L10A; uL1; CSA19
Tractability: Small molecule: an approved drug acts on it; a structure with a bound ligand is known; a high-quality ligand is known. PROTAC: UniProt records ubiquitination sites on it; ubiquitination databases record sites on it; its protein half-life has been measured; a small molecule that binds it is known. Other modalities: a drug acting on it is in phase 2 or 3 trials.
Target class: Other cytosolic protein
Gene: Protein-coding gene on chromosome 6 (35,468,366 to 35,470,785, forward strand). Ensembl gene ENSG00000198755.
Subcellular location: Cytoplasm
Subcellular location (Human Protein Atlas): Cytosol; Endoplasmic reticulum; Nucleoli
Pathways (Reactome):
Metabolism of proteins: Eukaryotic Translation Termination; Formation of a pool of free 40S subunits; GTP hydrolysis and joining of the 60S ribosomal subunit; L13a-mediated translational silencing of Ceruloplasmin expression; PELO:HBS1L and ABCE1 dissociate a ribosome on a non-stop mRNA; Peptide chain elongation; Ribosome Quality Control (RQC) complex extracts and degrades nascent peptide; SRP-dependent cotranslational protein targeting to membrane; ZNF598 and the Ribosome-associated Quality Trigger (RQT) complex dissociate a ribosome stalled on a no-go mRNA
Metabolism of RNA: Major pathway of rRNA processing in the nucleolus and cytosol; Nonsense Mediated Decay (NMD) enhanced by the Exon Junction Complex (EJC); Nonsense Mediated Decay (NMD) independent of the Exon Junction Complex (EJC)
Cellular responses to stimuli: Response of EIF2AK4 (GCN2) to amino acid deficiency
Developmental Biology: Regulation of expression of SLITs and ROBOs
Disease: Viral mRNA Translation
Metabolism: Selenocysteine synthesis
Gene Ontology:
Molecular function: protein binding; RNA binding; structural constituent of ribosome
Biological process: cytoplasmic translation; negative regulation of myoblast fusion; spermatogenesis; striated muscle contraction; translation; response to ethanol
Cellular component: cytoplasm; cytosol; cytosolic large ribosomal subunit; cytosolic ribosome; endoplasmic reticulum; extracellular exosome; focal adhesion; membrane; nucleolus; nucleus; large ribosomal subunit; postsynaptic density
Genetic constraint (gnomAD): Loss-of-function variants: 11 observed, 25.3 expected, observed/expected ratio (o/e) 0.43, 90% interval 0.27 to 0.72. The upper end of that interval is the gene's LOEUF score, 0.72, which puts it in group 2 of 6, group 1 being the genes least tolerant of losing a copy. Missense variants: 136 observed, 268.8 expected, observed/expected ratio (o/e) 0.51, 90% interval 0.44 to 0.58. Synonymous variants: 98 observed, 107.85 expected, observed/expected ratio (o/e) 0.91, 90% interval 0.77 to 1.08.
Homologues: Orthologues: chimpanzee RPL10A (100% identical), dog RPL10A (100% identical), guinea pig RPL10A (100% identical), macaque RPL10A (100% identical), mouse Rpl10a (100% identical), rat Rpl10a (100% identical), pig RPL10A (99% identical), tropical clawed frog rpl10a (94% identical), zebrafish rpl10a (92% identical), Drosophila melanogaster RpL10Ab (77% identical). Paralogues in human: RPL7A (21% identical), RSL1D1 (21% identical), NHP2 (6% identical).
Diseases named in the same sentence as RPL10A in open-access papers:
RPL10A is named in the same sentence as 31 diseases in open-access papers, as found by Europe PMC text mining. Sharing a sentence is not in itself a finding about the gene and the disease. The quoted sentences say what the papers report.
breast carcinoma (3 papers, 2021 to 2025). "To understand how different types of interacting cells respond to metabolically challenging conditions, we exposed co-cultures of breast cancer cells (SUM-159PT-GFP-RPL10a) and fibroblasts (MRC5-mCherry-RPL10a) to limiting concentrations of glucose." (PMID 40389477, 2025). "In a previous report, Fang and Zhang used integrated bioinformatics analyses and identified that low mRNA expression of RPL11, RPS14, RPS9, and RPL10A were related to a worse overall survival of breast cancer patients." (PMID 33718123, 2021). "Different from our findings of RPL10A as a protective prognostic marker, low-expression of RPL10A was associated with worse OS and RFS of patients with glioblastoma and worse OS of patients with breast cancer." (PMID 34434692, 2021). "Simultaneously, we engineered a mouse tumor cell line (E0771) derived from spontaneous breast cancer in C57BL/6 mice, where the endogenous Rpl10a gene was homozygously tagged at the N-terminus with GFP." (PMID 40389477, 2025).
neuroblastoma (2 papers, 2021 to 2023). Neuroblastoma (NB) is the most common solid, extracranial childhood tumor. "Other proteins linked to metabolism such as eEF2, PFKP, GAPDH and ribosomal protein L10a were also confirmed to be enriched in the EVs secreted by MYCN-positive neuroblastoma cells." (PMID 34847775, 2021).
anemia (1 paper, 2019). A reduction in the number of red blood cells, the amount of hemoglobin, and/or the volume of packed red blood cells. "Overall, the results suggested that Rpl10a deficiency caused delays in embryonic development, as well as apoptosis and anemia, in zebrafish." (PMID 31792295, 2019). "The qPCR results showed that these genes, which are involved in erythroid synthesis, had low expression in Rpl10a-deficient embryos, suggesting that it might play a role in anemia." (PMID 31792295, 2019).
glaucoma (1 paper, 2022). Increased pressure in the eyeball due to obstruction of the outflow of aqueous humor. "For example, CDCA8, HLA-B, RHOC, PPM1J, RPL10A, and TEAD3 are associated with glaucoma (P < 1 × 10−6)." (PMID 36450729, 2022).
ischemia (1 paper, 2025). A hypoperfusion of the BLOOD through an organ or tissue caused by a PATHOLOGIC CONSTRICTION or obstruction of its BLOOD VESSELS, or an absence of BLOOD CIRCULATION. "The expression of RPL10A, RPL14, RPL30, RPS18, FAU-40 (RPS30), and RPSA (Laminin Receptor, LR) was assessed in the myocardial and EAT tissues of MI, CABG and HL swine models and in LVSCs and EATDS challenged with ischemia." (PMID 39641799, 2025). "Importantly, the EATDS-derived exosomes have been unveiled for their potential cardiac responses and our previous findings identified major ribosomal proteins including RPL10A, RPL14, RPL30, RPS18, FAU-40 (RPS30), and RPSA (Laminin Receptor, LR) in the vesicles of ischemia-challenged EATDS." (PMID 39641799, 2025).
sarcoidosis (1 paper, 2017). Sarcoidosis is a multisystemic disorder of unknown cause characterized by the formation of immune granulomas in involved organs. "Additionally, both RPSA and RPL10A genes encoding ribosomal proteins were found to be significantly downregulated in sarcoidosis monocytes as compared to healthy monocytes." (PMID 28577019, 2017).
triple-negative breast carcinoma (1 paper, 2025). An invasive breast carcinoma which is negative for expression of estrogen receptor (ER), progesterone receptor (PR), and human epidermal growth factor receptor 2 (HER2). "To accomplish this in the triple-negative breast cancer (TNBC) cell line SUM-159PT, we introduced N-terminal tags of GFP, mCherry, or mNeonGreen into the RPL10a gene through gene editing, achieving homozygous expression." (PMID 40389477, 2025).
viral infection (1 paper, 2008). "A question that remains unanswered is how phosphorylated rpL10A functions to impact viral infectivity leading to a delay in the onset of virus infection." (PMID 19112492, 2008). "In other independent experiments, the infectivity data, expressed as DPI50% (days postinoculation to reach 50% of infected plants), further confirmed that rpl10a and nik1 displayed the similar enhanced efficiency of virus infection as compared to Col-0." (PMID 19112492, 2008). "Phosphorylation of cytosolic rpL10A by NIK1 redirects the protein to the nucleus where it may act to modulate viral infection." (PMID 19112492, 2008). "Alternatively or additionally, as a putative translational control factor, redirecting rpL10A to the nucleus may shut down protein synthesis, thereby impairing virus infection." (PMID 19112492, 2008).
Wilms tumor (1 paper, 2008). An embryonal neoplasm characterized by the presence of epithelial, mesenchymal, and blastema components. "The rpL10A gene (At1g14320) is closely related to QM originally identified from the Wilms' tumor cell line as a candidate tumor-suppressor gene and has been shown to regulate the proto-oncogene c-Yes." (PMID 19112492, 2008).
infection (7 papers, 2008 to 2022). The state of being infected such as from the introduction of a foreign agent such as serum, vaccine, antigenic substance or organism. "Loss of rpL10A function recapitulated the nik1 enhanced susceptibility phenotype to geminivirus infection, as the rpl10a knockout lines developed similar severe symptoms and displayed similar infection rate as nik1." (PMID 19112492, 2008). "At 8 h post-infection, trachea responses were more different between LPAI- and HPAI-infection but some genes have potential similar functions (for example ribosomal protein L10a, L7a and LP2)." (PMID 24015922, 2013). "To distinguish between these possibilities we attempted to develop a transient infection assay to determine whether geminivirus would interfere with the NIK1-driven nuclear relocalization of rpL10A as a counterdefensive measure." (PMID 19112492, 2008). "Astrocytes of neuron-glia cocultures were filled with EGFP by infection with LVGFAPEGFP, and Rpl10a signal intensities were analyzed within the EGFP mask." (PMID 26690742, 2015). "In fact, CP null mutants of CaLCuV DNA-A delays infection and attenuates symptoms in wild type lines but not in nik1 or rpl10a knockouts in which the coat protein-less mutant promotes wild type-like infection." (PMID 19112492, 2008).
cancer (3 papers, 2016 to 2022). A tumor composed of atypical neoplastic, often pleomorphic cells that invade other tissues. "Consistent with our KEGG analysis, the downregulation of several genes that encode protein components of the ribosome (RPL8, RPS8, and RPL10A) in plasma is associated with cancer." (PMID 35816095, 2022). "Since RPL21 and RPL10A are highly expressed in cancer, we confirmed their upregulation in our model of tumorigenesis." (PMID 27551510, 2016). "Additionally, the centrality of Wnt signaling to not only embryogenesis but also adult tissue maintenance and cancer raises the question of whether RPL10A/uL1-mediated translational control of Wnt signaling components may also play important roles in these processes." (PMID 36123354, 2022).
cardiovascular disease (1 paper, 2024). "RPL21, RPL26, and RPL10A are important components of the large 60S ribosomal subunit with functions involved in cell proliferation, differentiation, apoptosis, and DNA repair, which have been associated with metabolism and cardiovascular disease progression." (PMID 38503760, 2024).
RPL10A also shares sentences with these, for which no sentence is quoted: B cell lymphoma (4 papers); lymphoma (3); tumor (3); T cell lymphomas (2); acute leukemia (1); acute lymphocytic leukemias (1); amyloid (1); chronic myeloid leukemia (1); COVID-19 (1); gastric cancer (1); glioblastoma (1); glioma (1); hepatoblastoma (1); histiocytic sarcoma (1); leukemia (1); lymphoid tumour (1); prion disease (1); prostate carcinoma (1); T-cell acute leukemia (1).